HMHB1 (histocompatibility minor HB-1)
Description:
Precursor of the histocomplatibility antigen HB-1. More generally, minor histocomplatibility antigens (mHags) refer to immunogenic peptide which, when complexed with MHC, can generate an immune response after recognition by specific T-cells. The peptides are derived from polymorphic intracellular proteins, which are cleaved by normal pathways of antigen processing. The binding of these peptides to MHC class I or class II molecules and its expression on the cell surface can stimulate T-cell responses and thereby trigger graft rejection or graft-versus-host disease (GVHD) after hematopoietic stem cell transplantation from HLA-identical sibling donor. GVHD is a frequent complication after bone marrow transplantation (BMT), due to mismatch of minor histocomplatibility antigen in HLA-matched sibling marrow transplants. HB-1 is presented on the cell surface by MHC class I HLA-B44. This complex specifically elicits donor-cytotoxic T lymphocyte (CTL) reactivity in B-cell acute lymphoblastic leukemia (B-ALL) after treatment by HLA-identical allogenic bone marrow transplantation (BMT). It induces cell recognition and lysis by CTL. However, HB-1 restricted expression in B-ALL cells and not in normal tissues may allow a specific CTL reactivity against B-ALL without the risk of evoking graft-versus-host disease.
Synonyms: HB-1; HB-1Y; HLA-HB1
Tractability: No criterion of Open Targets' tractability assessment is met for any kind of drug.
Gene: Protein-coding gene on chromosome 5 (143,812,147 to 143,820,716, forward strand). Ensembl gene ENSG00000158497.
Gene Ontology:
Biological process: cellular response to tumor necrosis factor; positive regulation of type II interferon production; regulation of gene expression
Genetic constraint (gnomAD): Loss-of-function variants: 2 observed, 1.45 expected, observed/expected ratio (o/e) 1.38, 90% interval 0.44 to 1.92. That is too few expected variants to judge how well the gene tolerates losing a copy. Missense variants: 13 observed, 10.98 expected, observed/expected ratio (o/e) 1.18, 90% interval 0.77 to 1.79. Synonymous variants: 2 observed, 2.83 expected, observed/expected ratio (o/e) 0.71, 90% interval 0.28 to 1.77.
Homologues: Orthologues: chimpanzee HMHB1 (98% identical), macaque HMHB1 (85% identical).
Diseases named in the same sentence as HMHB1 in open-access papers:
HMHB1 is named in the same sentence as 2 diseases in open-access papers, as found by Europe PMC text mining. Sharing a sentence is not in itself a finding about the gene and the disease. The quoted sentences say what the papers report.
cancer (2 papers, 2024 to 2025). A tumor composed of atypical neoplastic, often pleomorphic cells that invade other tissues. "There are plenty of other potential non-coding genes that are likely cancer antigens, including HMHB1, DCANP1 and PRAC2." (PMID 39713347, 2024).
HMHB1 also shares sentences with these, for which no sentence is quoted: genetic disease (1 paper).